INS (insulin)
Diseases named in the same sentence as INS in open-access papers (continued):
Sharing a sentence is not in itself a finding about the gene and the disease.
diabetes (continued). "Specific medication management advice for oral glucose lowering therapies, insulin, and other parenteral agents (e.g. GLP-1 agonists, amylin analogs) is paramount for safe fasting by diabetes patients." (PMID 24606885, 2014). "The assay performance was validated by investigating six of the known monogenic diabetes genes (HNF4A, GCK, HNF1A, HNF1B, INS and KCNJ11) in 70 Danish patients carrying previously identified causative variants." (PMID 24476040, 2014). "Whether or not exogenous insulin can alter microbiota composition and/or obscure diabetes-associated changes in microbiota composition is unknown, however future studies could explore this issue by studying diabetic cats at the time of diagnosis, prior to commencement of insulin therapy." (PMID 25279695, 2014). "They measured insulin secretion (glucagon-stimulated C-peptide) and insulin action (short intravenous insulin tolerance test) in T2DM, T1DM, and ketosis-prone diabetes (KPD) groups during a 10-year followup." (PMID 24829925, 2014). "LFS was calculated based on the AST/ALT ratio, diabetes, fasting AST level, fasting insulin level, and MetS." (PMID 25204761, 2014). "Therefore, diabetes and Aβ could synergistically affect insulin signaling." (PMID 25250014, 2014). "Diabetes mellitus (DM) is a group of heterogeneous, hormonal, and metabolic disorders characterized by hyperglycemia and glucosuria, resulting from defects in insulin secretion, insulin action, or both." (PMID 25349608, 2014). "Sixty-two patients (48.0%) took OHA as treatment for their diabetes, while 12 (9.3%) took insulin alone, and 28 (21.7%) took OHA + insulin." (PMID 24789071, 2014). "Streptozotocin (STZ) treatment destroys the beta insulin-producing cells of the pancreas and STZ-induced diabetic rats are considered as a model of type 1 diabetes mellitus." (PMID 25215302, 2014). "Moreover, insulin and dopamine may exert reciprocal regulation between PD and diabetes." (PMID 24465703, 2014). "Each group had nearly 20% of patients with diabetes mellitus, and 29 (85.3%) patients in normal Lp-PLA2 group and 20 (83.3%) patients in elevated Lp-PLA2 group were treated with insulin and the rest (14.7% vs 16.7%, P = 0.283) were treated with sulfonylureas." (PMID 24580749, 2014). "Because HSP90 may be involved in the insulin signalling pathway in T2D muscles or can be a consequence of type 2 diabetes and may be sign of oxidative stress which is induced by chronic hyperglycaemia, our results may potentially be important for diabetes research." (PMID 24689038, 2014). "Since the emergence of PIT as a promising cure therapy of diabetes, efforts aimed at making PIT a more competitive alternative to insulin injections have focused on improving the longevity and functionality of islet grafts." (PMID 24829922, 2014). "We also provide biochemical characterization of RSL polyphenols and report on the acute glucose lowering and insulin sensitizing activity of the RSL leaf powder in a mouse model of diet-induced obesity and diabetes." (PMID 24637790, 2014). "In an animal model of T1DM where rodents were induced to develop diabetes through streptozotocin (STZ), MSC were able to differentiate into insulin-producing cells, releasing insulin in a glucose dependant manner and improving diabetic symptoms." (PMID 24936198, 2014). "Approximately half of the residents with diabetes included in the current study received prescriptions for any antidiabetic medications which included OAD and/or insulin during a 90-day window of observation." (PMID 24719761, 2014). "The reverse is also true, with increases in fasting blood glucose and insulin levels leading to a higher overall prevalence of NAFLD, which is estimated to be 63–69% in patients with diabetes." (PMID 24595017, 2014).
diabetes (continued). "A tool for Genome-wide Complex Trait Analysis (GCTA) was used to estimate the genome-wide GxE variance contribution of four diabetes-related traits: HOMA-Insulin Resistance (HOMA-IR), fasting plasma insulin, glucose and adiponectin." (PMID 25213455, 2014). "A potential cause of diabetes may be dysfunctional insulin-secreting pancreatic β-cells that do not have the capacity to secrete insulin; additionally, glucose metabolism dysfunction, specifically glucose production and glucose uptake, may play a role in this disease." (PMID 25013896, 2014). "Similar observations show that insulin sensitizers may have beneficial effects on AD, and these benefits may be offset later by longer exposure to DM, further supporting the idea that duration of diabetes may play an important role in AD pathogenesis." (PMID 24489845, 2014). "FPG levels, fasting insulin levels, HOMA-IR, TC, TG and LDL-cholesterol levels were higher while HOMA-ß and HDL-cholesterol levels were lower in subjects with incident diabetes." (PMID 24587359, 2014). "The Diabetes Control and Complication Trial (DCCT) was a clinical trial aimed at comparing intensive treatment, i.e., at least 3 insulin injections a day, to the traditional treatment, once or twice a day for Type 1 diabetes mellitus (T1DM) patients." (PMID 25473827, 2014). "Negative attitudes towards insulin are commonly reported by people with type 2 diabetes mellitus (T2DM) and can act as a barrier to timely insulin initiation." (PMID 24902877, 2014). "The insulin/IGF pathway, which is usually hyper activated in obesity and diabetes, is a major player in the chain of events linking the metabolic syndrome with cancer." (PMID 24904527, 2014). "With regard to diabetes management, 150 (98%) were taking antidiabetic agents of which 72 (47.1%) were on a combination regimen of OHA and insulin." (PMID 25435876, 2014). "Since GLP‐1‐based drugs and sulfonylurea compounds are important insulin secretagogues and widely used clinically in diabetes, we studied the effect of BLX‐1002 on GLP‐1‐ and tolbutamide‐induced insulin secretion." (PMID 24872354, 2014). "The identification of AMP-activated protein kinase (AMPK) phosphorylation as a likely mechanism is particularly interesting in relation to diabetes and obesity because activation of AMPK inhibits lipid synthesis and can improve insulin action." (PMID 24550994, 2014). "The percentage of insulin+ β-cells expressing Ki67 was 0.25±0.18% in pancreata of new-onset diabetic NOD mice and greatly decreased with diabetes duration (0.014±0.014% in pancreases from long-standing diabetics)." (PMID 25268801, 2014). "GLP-1 is one of target molecules for the treatment of Type 2 diabetes mellitus because it activates the GLP-1 receptor on the cell and then mediates insulin secretion." (PMID 24688594, 2014). "Moreover, urotensin 2 inhibits insulin release, has inotropic and hypertrophic effects on heart muscle, and is a proposed biomarker of cardio-metabolic disorders including hypertension, atherosclerosis, heart failure, pulmonary hypertension, diabetes, renal failure and metabolic syndrome." (PMID 24643011, 2014). "Type 2 diabetes mellitus (T2DM) is a progressive disease resulting from increasing insulin resistance and reduced pancreatic β-cell insulin secretion." (PMID 25539584, 2014). "PGC-1 alpha activates the expression of insulin-sensitive GLUT4 in skeletal muscle and plays a role in preventing insulin resistance and type 2 diabetes mellitus." (PMID 25414671, 2014). "In young (4 wk old) diabetes-prone NOD mice, glucagon-, insulin- and somatostatin-positive cells comprised most of the islet area (84.9±1.8%)." (PMID 25101835, 2014). "As expected, the hospital unit costs have the highest impact on the total cost of T2DM, but also the likelihood of developing diabetes (incidence) and the cost of medication (OAD and insulin) have a major impact." (PMID 26208925, 2014).
diabetes (continued). "Similar to women, who develop diabetes, the regression line of IGFBP1 on insulin in women born SGA was suppressed below that in women with normal OGTT over a decade." (PMID 23781317, 2013). "Type 2 diabetes mellitus (T2DM) is a heterogeneous, multifactorial, polygenic disease characterized by a defect in either insulin secretion and/or action that results in elevated circulating glucose." (PMID 24167617, 2013). "The findings suggest poor glycaemic control and suboptimal diabetes management across many geographical regions, which may be due to poor adherence to treatment regimens, lack of access to therapy, poor diet, and delay in initiating, or failure to adequately optimise, insulin therapy." (PMID 24228724, 2013). "The regression line for IGFBP1 on insulin in the term SGA women was suppressed below the reference material by −1 s.d., a pattern previously noticed in women who later developed diabetes." (PMID 23781317, 2013). "FFA is one of the key factors that influences insulin activity and elevated FFA levels are predictive of the progression from impaired glucose tolerance to diabetes." (PMID 23983807, 2013). "The top diabetes-related antigens were GAD, insulin, IA-2/PTPRN, IGRP, ZnT8, HSP, and ICA-1, representing nearly 90% of the captured data." (PMID 25140192, 2013). "We propose that currently emerging approaches to provide treat-to-target insulin therapy during the pre-diabetic stage in order to suppress endogenous insulin production and ER-crowding, may benefit patients with pre-diabetes without significant rise in treatment related risk." (PMID 23408938, 2013). "Insulin, which has long been considered last-line therapy in the treatment of T2DM and is the primary treatment of Type 1 Diabetes Mellitus (T1DM, insulin-dependent DM), is now a viable addition to metformin as a second-line agent in lieu of sulfonylureas." (PMID 23737828, 2013). "Since levels of PAI-1 increase in endothelial cells as a result of exposure to high glucose, high insulin, oxidative stress, or TGF-β1, we measured endogenous secretion of PAI-1 in CD34+ cells from individuals with diabetes." (PMID 24223881, 2013). "Glucose homeostasis is regulated by several polypeptides such as insulin, adiponectin, glucagon-like peptide–1 (GLP-1), and many others making them attractive candidates for the treatment of diabetes." (PMID 23648189, 2013). "Intensive insulin therapy is used clinically to obtain satisfactory glycemic control in patients with both Type 1 (T1DM) and advanced Type 2 diabetes mellitus (T2DM) in order to avoid long-term complications of hyperglycemia." (PMID 23894333, 2013). "Our data showed that induction of diabetes by STZ led to a significant increase of plasma glucose and a significant decrease in plasma insulin and C-peptide levels compared to the basal levels." (PMID 24279645, 2013). "Thus, LEA rats may serve as a new model of nonobese type 2 diabetes mellitus caused by impairing insulin secretion." (PMID 23691528, 2013). "Key inclusion criteria were: type 1 or 2 diabetes, major depression (diagnosed with the Structured Clinical Interview for DSM-IV, SCID) and hemoglobin A1C >7.5% despite current insulin therapy." (PMID 23915015, 2013). "We developed a simple and new insulin resistance index derived from a glucose clamp and a meal tolerance test (MTT) in Japanese patients with type 2 diabetes mellitus." (PMID 23339473, 2013). "In this article we report the findings from a randomized controlled trial evaluating the effect of Jiangtang Xiaozhi on blood glucose, insulin and lipids in people with IGT and controlled diabetes." (PMID 23672597, 2013). "More than 200 immune interventions have been described to prevent diabetes in NOD mice and a few have restored insulin secretion." (PMID 23555060, 2013). "The relevant pharmacological mechanism of glyburide in diabetes is the inhibition of KATP-channels in pancreatic β-cells, which leads to the stimulation of insulin secretion." (PMID 24147174, 2013).
diabetes (continued). "Hence, they used 0.2% chitosan reduced gold nanoparticles for loading of insulin because of the best zeta potential, stability (6 months) and viscosity of the various gold nanoparticles prepared from these, which showed effective glucose control in diabetes in rats." (PMID 23468918, 2013). "Cross-sectional human studies have shown that insulin resistance (IR) (i.e., co-existence of high blood glucose and insulin levels) is a consistent finding in patients with type 2 diabetes mellitus (DM), and a close interaction between DM and HCC has been documented." (PMID 23708326, 2013). "The aim of the present study was to assess the efficiency of the long-term use of continuous subcutaneous insulin infusion (CSII), a novel regimen known as insulinization, for the treatment of type 2 diabetes mellitus." (PMID 24223662, 2013). "Low-dose insulin deactivated p44/42 MAPK and ameliorated peripheral sensory nerve dysfunction in rats with STZ-induced diabetes." (PMID 24023699, 2013). "Formerly known as insulin-dependent diabetes mellitus (IDDM), it occurs when the β-cells of the pancreatic islets of Langerhans are destroyed, such that insulin production is grossly impaired." (PMID 24228060, 2013). "Its inhibition enhances insulin signaling and attenuates insulin resistance both in conventional and non conventional insulin-responsive tissues, indicating PTP1B as a target for the development of novel therapeutics for diabetes and obesity." (PMID 23861927, 2013). "Overexpression of ICA69 in INS-1 cells reduced insulin secretion, while ICA69 knockout (KO) mice were resistant to cyclophosphamide-accelerated diabetes." (PMID 23630453, 2013). "The aim of this study was to examine possible growth-promoting effects of native human insulin, insulin X10 and IGF-1, which are considered positive controls in vitro, in a short-term animal model of an obesity- and diabetes-relevant cancer." (PMID 24260289, 2013). "Generally, patients with diabetes mellitus are treated with oral hypoglycaemic agents (OHA) and insulin." (PMID 23684219, 2013). "Type 2 diabetes mellitus (T2DM) is characterized by chronic hyperglycemia and defects in the secretion and/or actions of insulin." (PMID 23431394, 2013). "BDNF has been reported to influence fasting GLU levels and insulin sensitivity, and decreased levels of the serum BDNF were found in the patients with MetS and type 2 diabetes mellitus." (PMID 23967328, 2013). "Despite the overall lack of broad conformational epitope coverage, the existing data represent the major auto antigens of diabetes in humans, namely GAD, insulin, IA-2 and ZnT8." (PMID 25140192, 2013). "The reduction in gluconeogenic gene levels observed in exercised old animals is in accordance with Heled and co-authors, which showed that physical exercise enhances hepatic insulin signaling and inhibits PEPCK activity in diabetes-prone Psammomys obese." (PMID 23442260, 2013). "The specific inhibitors of PTP1B in this article are not only considered as potential pre-drugs for treating diabetes and obesity but also as probers to discover the effect of PTP1B in the insulin signaling pathway." (PMID 23774838, 2013). "Elucidating the regulation of glucose-stimulated insulin secretion (GSIS) in pancreatic islet β cells is important for understanding and treating diabetes." (PMID 23560115, 2013). "The insulin B9–23 domain, containing both, a dominant CD4 and a Kd-restricted B15–23 CD8 T-cell epitope, plays a prominent role in the diabetes development in NOD mice." (PMID 23977133, 2013). "Plasma insulin concentration and ISI were significantly higher in the HPS3-treated mice than in mice of the diabetes mellitus (DM) model control group." (PMID 23866043, 2013). "Hormone resistance to the effects of insulin, leptin, and fibroblast growth factor 21 (FGF21) has been reported in diabetes and obesity." (PMID 23409033, 2013).
diabetes (continued). "However, the validity of HOMA-IR may be limited in some patients, particularly those with a low BMI, decreased β cell function, and high fasting glucose levels, which are quite common in lean Korean patients with type 2 diabetes mellitus and insulin secretory defects, for example." (PMID 23339473, 2013). "It has been confirmed that the mechanisms of anti-diabetes involve in activation of AMPK and improvement of insulin sensitivity." (PMID 24205048, 2013). "As such, our objective is to evaluate the comparative effectiveness, safety and cost-effectiveness of DPP-4 inhibitors versus intermediate acting insulin for T2DM patients who have failed both first- and second-line diabetes treatments." (PMID 23810103, 2013). "Pharmacological activation of PPARγ improves insulin resistance in diabetes and has been reported to decrease liver damage in NAFLD by restoring adipose tissue insulin sensitivity, decreasing FFA flux to the liver." (PMID 23394097, 2013). "The study reported that RBP4 was elevated in insulin-resistant mice with adipose tissue-specific GLUT4 knockout and humans with obesity and type 2 diabetes mellitus." (PMID 24160775, 2013). "The clinical trials included in our meta-analysis are some of the first involving an injectable insulin to measure HRQoL, and advance the use of patient-reported outcomes (PRO) in evaluating the value of therapeutic innovations in patients with diabetes." (PMID 23451759, 2013). "Insulin resistance is one of the core defects in type 2 diabetes mellitus (T2DM) and this defect leads to hyperinsulinemia that compensates for the reduced efficacy of insulin in peripheral tissues." (PMID 23527159, 2013). "Insulin dependent diabetes mellitus (IDDM), type 1 diabetes, is a form of diabetes mellitus that results from autoimmune destruction of insulin-producing β-cell of the pancreas." (PMID 23691525, 2013). "In each of the diabetes subgroups, no statistically significant placebo-adjusted changes were observed in the diabetes end points of FPG, A1c, HOMA-IR, or insulin following treatment with IPE 4 g/day or 2 g/day." (PMID 23835245, 2013). "In support of this conclusion, a study in India on normal-weight offspring with type 2 diabetes mellitus that were matched with controls of comparable age showed that the former had lower plasma HDL-C concentrations and higher values of plasma insulin." (PMID 24267726, 2013). "The anti-inflammatory insulin sensitizer, HE3286, was tested for its ability to decrease obesity-related inflammation-induced insulin resistance and metabolic dysregulation in diabetes." (PMID 23431246, 2013). "Another more recent meta-analysis of up to 108,557 individuals of European ancestry without diabetes, including individuals newly genotyped using the Metabochip, have identified 17 additional loci with genome-wide significant association with fasting insulin concentration." (PMID 24392014, 2013). "Altogether, these findings suggest that the cross-talk between insulin AKT and Ang II signalling pathways plays a significant role in the co-occurrence of diabetes and hypertension." (PMID 24400038, 2013). "In this study, it was shown that the dyslipidemia associated with diabetes is not sufficient to initiate the atherosclerotic lesion, because the progression of atherosclerosis process could be normalized after intensive glycemic control with insulin in mice." (PMID 23533715, 2013). "Fewer diabetes-related PCP visits were completed post-CSII (5.09 vs 3.78 visits/year, p = 0.009), and less non-insulin diabetes medications were prescribed post-CSII (p < 0.001)." (PMID 27536441, 2013). "After 4 weeks of experimental diabetes, OVS and OVSE animals had a significant decrease of plasma insulin, a strong increase of blood glucose and HbA1c." (PMID 23209733, 2012). "Diabetes medications such as insulin and oral hypoglycemic agents (OHA) are for most individuals with diabetes the main therapeutic option for glycemic control." (PMID 22719972, 2012).